INS (insulin)
Diseases named in the same sentence as INS in open-access papers (continued):
Sharing a sentence is not in itself a finding about the gene and the disease.
diabetes (continued). "Among these, type 2 diabetes mellitus (T2DM) is the most prevalent, primarily characterized by high blood sugar levels due to the body’s insufficient insulin production or ineffective use of insulin." (PMID 40771269, 2025). "Type 2 diabetes mellitus (T2DM) is a chronic metabolic disorder characterized by impaired insulin secretion from pancreatic β-cells and reduced insulin sensitivity, leading to persistent hyperglycemia." (PMID 41246704, 2025). "Type 2 diabetes mellitus (T2DM) is a complex metabolic disorder in which insulin resistance and impaired insulin secretion are primarily driven by the patient’s overweight or obesity status." (PMID 40430501, 2025). "The induction of diabetes led to a significant increase in the levels of serum glucose (253a ± 7.1), HOMA-IR (5.5a ± 0.069), insulin (8.8a ± 0.3), and leptin (36a ± 2.10) compared to the control group." (PMID 40184394, 2025). "At 12 months post-GLP-1RA-initiation, the concomitant use of anti-diabetes agents was as follows: metformin, SGLT2 inhibitors, insulin, sulfonylureas, α-glucosidase inhibitors, glinides, and thiazolidinediones." (PMID 41040428, 2025). "Beyond insulin secretion, verapamil and other CCBs reduce the β-cell expression of thioredoxin-interacting protein (TXNIP), a proapoptotic factor overexpressed in diabetes, thereby inhibiting β-cell apoptosis and enhancing survival." (PMID 40710367, 2025). "In contrast, some studies suggested that long-term diabetes transitions towards reduced levels of Insulin, IGF-1, and testosterone over time, partially explaining the lower incidence of prostate cancer in men with diabetes." (PMID 41367482, 2025). "Functional CMD is more prevalent in non-insulin-dependent patients and the evidence seems to suggest that this disease can evolve into structural CMD as diabetes advances." (PMID 40004660, 2025). "Insulin therapy remains a cornerstone in the management of both type 1 (T1DM) and type 2 diabetes mellitus (T2DM)." (PMID 41293743, 2025). "In type 2 diabetes mellitus (T2DM), chronic inflammation damages the pancreatic β-cells leading to insufficient insulin secretion and subsequent hyperglycemia." (PMID 40864768, 2025). "Not many studies show long-term glycaemic control or a decrease in diabetes-related complications in human populations, even though some polymeric nanocarriers (such as those based on chitosan or PLGA) increase insulin bioavailability." (PMID 40574088, 2025). "In terms of treatment type, 41.6% of participants were managing their diabetes using oral hypoglycemic agents (OHA), 24.4% were using a combination of OHA and insulin, 21.8% relied on lifestyle modifications, and 12.2% were on insulin injections alone." (PMID 40677508, 2025). "Alternatively, participants with diabetes were also classified as having T1DM if they had a repeated C peptide below 0.6 nmol/L and received basal-bolus insulin treatment during the 2-year follow-up." (PMID 41225468, 2025). "Safe management of insulin across ToC required input from both the PWDI and a multidisciplinary team including community and hospital nurses, general practitioners, doctors, diabetes specialists and pharmacists among others." (PMID 40324886, 2025). "Type 1 diabetes mellitus (T1DM) is a common chronic disease, and there is a rising trend globally; insulin is the mainstay therapy." (PMID 40852189, 2025). "Age-dependent increase in glucose level and decrease in the level of insulin was noted in WBN/Kob rats, a strain that spontaneously develops type 2 diabetes mellitus at around six months of age." (PMID 40427746, 2025). "Type 1 diabetes mellitus (T1DM) is an autoimmune disorder characterized by the destruction of pancreatic β-cells, necessitating lifelong exogenous insulin." (PMID 41142642, 2025). "Inflammation has been established as a primary instigator of diabetes, and TNF‐α neutralization has been shown to improve insulin sensitivity." (PMID 39327931, 2025).
diabetes (continued). "Moreover, defective PI folding and maturation have been found in db/db mice as well as in patients with type 2 diabetes (T2D), suggesting that defects in early events of INS biosynthesis may contribute to the development and progression of mutant INS gene–induced diabetes and T2D." (PMID 40392602, 2025). "It was observed that patients who used OAD in the treatment of diabetes and followed a diet and exercise had better treatment adherence than those using OAD, insulin, and insulin and OAD." (PMID 39976636, 2025). "The following queries were used: ‘Quercetin’ and ‘diabetes’; ‘T2DM’; ‘T1DM’; ‘carbohydrate’; ‘glucose’; ‘hyperglycemia’; ‘insulin’; ‘retinopathy’; ‘nephropathy’; ‘macroangiopathy’." (PMID 40807271, 2025). "Long-term follow-up from the United Kingdom Prospective Diabetes Study (UKPDS) and the Diabetes Control and Complications Trial/Epidemiology of Diabetes Interventions and Complications (DCCT/EDIC) suggested that intensive glycemic control with insulin may reduce the risk of myocardial infarction." (PMID 41011236, 2025). "Type 2 diabetes mellitus (T2DM) is a chronic metabolic disorder characterized by insulin resistance, culminating in impaired insulin secretion and action." (PMID 41280372, 2025). "Diabetes is often classified into three types: People with Type 1 diabetes, also called insulin-dependent diabetes mellitus (IDDM), cannot make enough insulin." (PMID 40574088, 2025). "Supporting this, in the hyperglycemia insulin network effort (SHINE) trial, 80% of the patients had a history of diabetes, making the findings particularly relevant to diabetic individuals with acute ischemic stroke." (PMID 40868089, 2025). "Type 2 diabetes mellitus (T2DM) is an endocrine and metabolic disorder characterized primarily by insulin resistance (IR) and insufficient insulin secretion." (PMID 40809436, 2025). "Of the 164 patients (62.1%) diagnosed with diabetes, 13 were taking sodium-glucose cotransporter 2 (SGLT-2) inhibitors prior to admission, and 121 were insulin-dependent." (PMID 39764343, 2025). "Duration of diabetes, CVR-R, ACR, insulin use, GLP-1 receptor agonist use, NCV, amplitude and eMBC differed significantly across RSS groups." (PMID 40740761, 2025). "In type 2 diabetes mellitus (T2DM), key features include insulin resistance, elevated insulin levels in the blood, and hyperglycemia." (PMID 40724942, 2025). "The Pearson correlations analyses showed a significant correlation between VAI and cardiometabolic biomarkers; WHR, TG, insulin, and AIP in participants with obesity, and diabetes with obesity." (PMID 40095937, 2025). "Type 2 diabetes mellitus (T2DM) rat models have demonstrated that hypoglycemic effects, insulin sensitization, antioxidant activity, and PPARA upregulation are associated." (PMID 40870685, 2025). "Strengths of our study include the large population of people with type 2 diabetes on insulin therapies included, and the fact that the NDR, SPDR and NPR have greater than 90% coverage of all adults with diabetes in Sweden." (PMID 39460755, 2025). "Similar to what was found in db/db mice, induced diabetes in BALB/c mice using STZ and treating with insulin showed that CTSL, the host protease that exposed the Spike fusion peptide, mRNA expression was increased in diabetic mice." (PMID 40572277, 2025). "The first domain was “knowledge,” which was consistent with the first step of successful diabetes self-management being patients’ knowledge about the disease and that a reason for low adherence to insulin therapy is poor knowledge of DM and insulin self-injection." (PMID 40242444, 2025). "A meta-analysis indicated that VE significantly improves levels of hemoglobin A1c, fasting insulin, and HOMA-IR in patients with Type 2 Diabetes Mellitus (T2DM)." (PMID 41373632, 2025).
diabetes (continued). "Thus, the identification of potential mechanisms whereby M. charantia L. improves insulin sensitivity could represent adjuvant nutrifunctional mechanisms in stimulating resistance to insulin in diabetes and related pathologies, such as obesity and dyslipidemias." (PMID 40941807, 2025). "Type 2 diabetes mellitus (T2DM), a metabolic disorder that presents with chronic hyperglycemia and an inadequate response to circulating insulin by peripheral tissues (insulin resistance), accounts for approximately 90% of global cases." (PMID 41302143, 2025). "Type 2 diabetes mellitus (T2DM), a chronic condition commonly observed in adults, particularly among the elderly, is characterized by a dysfunctional insulin response that impairs blood glucose regulation, resulting in persistent hyperglycemia." (PMID 40432897, 2025). "In Italy, insulin pumps (both conventional and patch-pumps) are reimbursed by the NHS for all individuals with insulin-treated diabetes mellitus." (PMID 41036118, 2025). "Compared to the LFD group, the HFD group developed insulin resistance, as shown by increased glucose concentration along with AUC from ITT, as well as increased serum insulin levels and HOMA-IR, indicative of diabetes." (PMID 40732915, 2025). "Type 2 diabetes mellitus (T2DM), a frequent co-occurring condition in obesity, is characterized by elevated blood sugar levels due to insulin resistance as well as impaired function of the insulin-producing pancreatic beta cells." (PMID 40537773, 2025). "Type 2 diabetes mellitus (T2DM) is a chronic disease with high blood glucose levels accompanied by disordered insulin secretion, low insulin sensitivity, and high insulin resistance." (PMID 40507062, 2025). "Type 2 Diabetes Mellitus (T2DM) is a prevalent metabolic disorder characterized by a combination of insulin resistance and impaired insulin secretion from pancreatic β-cells, leading to chronic hyperglycemia." (PMID 40282289, 2025). "Overall, hyaluronic acid holds significant promise in advancing insulin delivery systems, offering controlled release, enhanced stability, and improved absorption, particularly for oral administration, which could lead to more effective and patient-friendly diabetes management." (PMID 40352348, 2025). "Non-insulin-dependent diabetes mellitus (NIDDM; type 2) progressively develops due to an imbalance between insulin secretion and insulin sensitivity within the body." (PMID 41146794, 2025). "The median age was 68 (IQR 56-72) years, 12 (71%) were males, the median diabetes duration was 18 (IQR 11-21) years, and 10 (59%) were treated with insulin." (PMID 40854092, 2025). "Factors including hypertension, diabetes mellitus, body weight, BMI, ALT, AST, albumin, triglycerides, fasting insulin, HDL-C, steatosis grade, and fibrosis stage were significantly associated with MASH (all p < 0.05)." (PMID 40361915, 2025). "Therefore, inhibiting key mediators of gluconeogenesis – such as glucose-6-phosphatase and fructose-1,6-bisphosphatase – alongside enhancing insulin production (which naturally suppresses gluconeogenic enzymes), may represent an effective approach to diabetes management." (PMID 41142063, 2025). "In 1949, the discovery of insulin-degrading enzyme (IDE), a protease that breaks down the B chain of the insulin hormone, prompted studies of the potential use of IDE inhibitors (IDEIs) to control insulin levels in animal models of diabetes." (PMID 39714747, 2025). "This study aimed to analyze the feasibility of utilizing them for evaluating the individual need of introducing insulin therapy, combined with the C-peptide index (CPI), in patients with type 2 diabetes mellitus (T2DM)." (PMID 40710394, 2025). "Between SII groups, there were statistically significant mean or median differences in TC, LDL-C, INS, gender, age, race, marital status, ALT, AST, and diabetes (p < 0.05)." (PMID 40668793, 2025).
diabetes (continued). "For example, insulin treatments, in particular, are linked to heightened severity, as patients believe that insulin is prescribed when their diabetes does not respond to other treatments; this perception is accompanied by a fear that insulin could harm or poison their body." (PMID 39853664, 2025). "During fasting and diabetes, PDK4 is widely upregulated in major tissues, in response to insulin depletion and increased glucocorticoids and free fatty acids." (PMID 39966707, 2025). "In insulin-resistant conditions, VEGFA expression appears to be elevated in the circulation, possibly due to the impacts of diabetes and inflammation." (PMID 40427019, 2025). "PDAC-DM can resemble recent-onset type 2 diabetes early on, so dynamic testing may be required to uncover low β-cell output, higher insulin clearance, and inadequate postprandial glucagon suppression (α-cell dysregulation)." (PMID 41226286, 2025). "Other significantly enriched pathways, relevant to the context of diabetes, include Metabolic pathways, FoxO signaling pathway, AMPK signaling pathway, Insulin signaling pathway, and Insulin resistance pathway, among others." (PMID 39932930, 2025). "Limited data exist regarding typical insulin needs for pediatric HTG treatment, but in adults with diabetes an average of 55.8 h of IV insulin infusion was required to correct TG to less than 500 mg/dL." (PMID 40612706, 2025). "miR-103a-3p is upregulated in both T1D and T2D patients, where it plays a critical role in insulin signaling by targeting CAV1, a key regulator of the insulin receptor in both forms of diabetes." (PMID 40244147, 2025). "Type 1 diabetes mellitus (T1DM) is a chronic, complex metabolic disorder characterized by the destruction of insulin-producing pancreatic beta cells." (PMID 40217883, 2025). "Type 2 diabetes mellitus (T2DM) is a significant health concern characterized by hyperglycemia, insulin resistance, and impairment in insulin secretion." (PMID 41597354, 2025). "As evidenced by elevated insulin levels, HOMA-IR score and decreased QUICKI our model exhibited significant insulin resistance, a characteristic of type 2 diabetes mellitus." (PMID 41309777, 2025). "The field of diabetes technology, including insulin pumps, continuous glucose monitors (CGM) and their combination, is rapidly evolving, and use of insulin pumps is expanding in most countries." (PMID 39172172, 2025). "Is the use of continuous glucose monitoring (CGM) associated with improved glycemic outcomes and related adverse events in insulin-treated older adults with Alzheimer disease and related dementias (ADRD) and diabetes?" (PMID 41329488, 2025). "Recent findings reveal that obesity and its comorbidities, such as type 2 diabetes mellitus (T2DM), share common molecular mechanisms with AD, including insulin resistance and impaired insulin signaling." (PMID 40808704, 2025). "Given that hypertension and diabetes elevate the likelihood of developing sarcopenia, and considering the positive correlation between VOC exposure and both hypertension and diabetes, it is plausible that VOCs may elevate the risk of sarcopenia by influencing blood pressure and insulin resistance." (PMID 40664812, 2025). "Post-matching balance of the following case-mix variables was further verified: age, sex, duration of diabetes, HbA1c, FBG, BMI/SDS,and per-kg dose of basal and short-acting insulin." (PMID 41323155, 2025). "GLP-1RAs are particularly effective in treating Type 2 diabetes mellitus (T2DM) during its early stages, as they enhance insulin secretion." (PMID 41155553, 2025). "Diabetes was induced using intravenous STZ, followed by daily insulin injections for 3 months to achieve metabolic control comparable to human patients." (PMID 41030912, 2025). "The actions of GLP-1 on insulin and glucagon secretion inspired the development of several GLP-1 receptor (GLP-1R) agonists that have revolutionized treatment for obesity and diabetes." (PMID 41178720, 2025).
diabetes (continued). "Suppression of these miRNAs in recipient β-cells blocked exosome-mediated apoptosis and prevented diabetes development in NOD mice, leading to improved insulin levels, reduced insulitis scores, and diminished inflammation." (PMID 40244147, 2025). "Increased insulin and glucose exposure is likely a contributing factor to the upregulation of the SPHK-S1P axis in placentas affected by diabetes." (PMID 39940917, 2025). "Consequently, it is hypothesized that the potential harm resulting from prolonged anlotinib use, which excessively inhibits normal islet capillaries, outweighs the benefits of blocking increased blood supply, ultimately leading to abnormal insulin secretion and diabetes development." (PMID 40242243, 2025). "Furthermore, in the present study we adjusted for strong factors associated with obesity such as diabetes, hypertension, CCI comorbidity score, hyperlipidemia, and use of insulin that it is possible that some levels of obesity were captured and adjusted for46, yet residual confounding may remain." (PMID 40595354, 2025). "Type 2 diabetes mellitus (T2DM) is the most common form of the disease and is primarily characterized by a reduction in insulin sensitivity and, in severe cases, a reduction in insulin production." (PMID 40428172, 2025). "Type 1 diabetes mellitus (T1DM) is a chronic autoimmune disease driven by T-cells, leading to the gradual destruction of insulin-producing beta cells in the pancreas." (PMID 40215252, 2025). "Type 1 diabetes mellitus (T1DM) occurs as a result of the destruction of pancreatic beta cells by T cells, halting the production of insulin." (PMID 40586776, 2025). "Hormonal and Inflammatory Markers: Elevated serum insulin, HbA1c, and C-reactive protein (CRP) levels were observed, indicating disrupted glucose metabolism and systemic inflammation, key contributors to diabetes and CVD." (PMID 41459237, 2025). "SCD, a key enzyme in fatty acid metabolism, has been demonstrated to prevent obesity and diabetes in HFD-fed mice, improving their lipid metabolic status and insulin sensitivity." (PMID 40458826, 2025). "Type 2 diabetes mellitus (T2DM) is a complicated disease defined by many metabolic abnormalities, such as impaired glucose metabolism and an aberrant hepatic insulin signaling pathway." (PMID 39846548, 2025). "Type 1 Diabetes Mellitus (T1DM) is a chronic autoimmune disorder characterized by immune-mediated destruction of pancreatic beta-cells (β-cells), leading to impaired insulin production or function." (PMID 40429939, 2025). "Type 1 diabetes mellitus (T1DM) occurs when a patient’s own immune system antibodies attack and destroy insulin-producing β-cells in the pancreas, resulting in less insulin production; however, it is unclear what exactly causes T1DM." (PMID 40937409, 2025). "Within this landscape, Automated insulin delivery (AID) systems have emerged as notable innovations, with the potential to revolutionize diabetes management, particularly in populations such as pregnant women with T1DM." (PMID 39792171, 2025). "Also, the signaling pathways contributing to deterioration of immune tissues, such as insulin signaling, play a critical role in metabolic dysfunctions and tumorigenesis, making them valuable targets for therapeutic intervention in diseases such as diabetes and cancer." (PMID 41178737, 2025). "According to the findings of the present study, it was determined that patients who used OAD in the treatment of diabetes and followed diet and exercise showed better treatment adherence than patients who used OAD and insulin therapy." (PMID 39976636, 2025). "Type 2 diabetes mellitus (T2DM) is a long-term metabolic disorder defined by insulin resistance and defective insulin secretion, leading to sustained hyperglycemia." (PMID 40861594, 2025).